TNF (tumor necrosis factor)
Diseases named in the same sentence as TNF in open-access papers (continued):
Sharing a sentence is not in itself a finding about the gene and the disease.
incontinence (5 papers, 2012 to 2025). "It has been proposed that IL-1α and TNF-α could serve as biomarkers of skin damage caused by urinary incontinence." (PMID 35053737, 2022). "Thus, urethral fibrosis due to inflammation (TNF-α) may be a risk factor for incontinence among certain demographic groups following radiation treatment." (PMID 39538179, 2024). "The reduced melatonin levels observed in this group of pregnant women correlated positively with IL-10 and inversely with TNF-α, reinforcing the possibility that urinary incontinence may result from a defective biological effect of melatonin." (PMID 41295285, 2025).
intracranial hypertension (5 papers, 2014 to 2024). A finding characterized by increased cerebrospinal fluid pressure within the skull. "This indicated that intracranial hypertension induced overexpression of TNF-α and activated the NF-κB/iNOS signaling pathway in the injured brain tissues." (PMID 38914585, 2024). "To understand whether the intracranial hypertension can activate the TNF-α/NF-κB/iNOS signaling pathway, we evaluated key markers of this pathway using IHC-P." (PMID 38914585, 2024). "Serum and cerebrospinal fluid (CSF) content of IL-8 and, to a lesser extent, tumor necrosis factor (TNF)-α demonstrated the most promise to be candidate serum markers of impending intracranial hypertension and cerebral hypoperfusion after TBI with proteomic mapping." (PMID 25741315, 2015). "Animal experiments reflect these interlinks at the molecular level, as intracranial hypertension augments the inflammatory response in ARDS, characterized by increased levels of TNFα, IL-6 and IL-1β, and microglial activation." (PMID 33163005, 2020).
Intraventricular hemorrhage (5 papers, 2016 to 2025). Bleeding into the ventricles of the brain. "They showed that cyclooxygenase-2, prostanoid receptor-1, or tumor necrosis factor-α inhibition reduced inflammatory cell infiltration, apoptosis, neuronal degeneration, and gliosis around the ventricles of studied pups with intraventricular hemorrhage." (PMID 27541865, 2016). "On the other hand, cyclooxygenase-2-inhibition or suppression of downstream molecules prostanoid receptor-1 or TNF-alpha might constitute neuroprotective strategy for minimizing brain damage in premature infants with intraventricular hemorrhage." (PMID 27541865, 2016). "Moreover, prostanoid receptor-1 and tumor necrosis factor-α were downstream to cyclooxygenase-2 in the inflammatory cascade induced by intraventricular hemorrhage." (PMID 27541865, 2016).
invasive carcinoma (5 papers, 2017 to 2025). A carcinoma that is not confined to the epithelium, and has spread to the surrounding stroma. "Higher TNF‐α levels were observed in invasive carcinomas compared to benign tissues, with their expression increasing alongside the tumor grade." (PMID 40685820, 2025). "Another finding that the genes significantly up/downregulated in the early-stage invasive carcinoma were significantly enriched for components of the TNFα- and IL1- signaling pathways suggests the inducing role of the inflamed microenvironment." (PMID 32899940, 2020). "In these invasive carcinomas the mechanism of tumor control likely depends on TNFα and type I IFN production by host cells, in particular via myeloid cells in the tumor environment, which in turn initiate and propagate adaptive anti-tumor immune responses." (PMID 29135982, 2017). "Previously collected plasma samples from patients with benign breast disease, in situ carcinoma, invasive carcinoma with no lymph node involvement (Inv/LN−), and invasive carcinoma with lymph node involvement (Inv/LN+) were evaluated by ELISA for CMV IgG, cmvIL-10, and human cIL-10, IL-6, and TNFα." (PMID 39172306, 2024).
lepromatous leprosy (5 papers, 2014 to 2023). A chronic communicable infection which is a principal or polar form of leprosy. "It has also been reported that anti-TNF therapy is associated with development of lepromatous leprosy and T1R." (PMID 36972292, 2023). "Patients with lepromatous leprosy have been demonstrated to have downregulated immune response due to lower tumor necrosis factor (TNF)-alpha and chemokine response, which can be a risk factor for the development of TB." (PMID 32669124, 2020).
liposarcoma (5 papers, 2012 to 2024). A usually painless malignant tumor that arises from adipose tissue. "Particularly, H3K9me2 has been reported as an epigenetic regulator of TNFα, IL-6, and IL-1β in the human-derived liposarcoma cell line SW872 stimulated with LPS." (PMID 39768289, 2024). "In liposarcoma cells, TNF-α strongly stimulated MMP-9 and showed slight up and down activity on MMP-2." (PMID 24085323, 2013). "In vivo, the combination of TNF-α, SMAC mimetics and melphalan induced tumour shrinkage, promoted the activation of CD8+ T cells as well as NK cells and prolonged survival in a rat model of liposarcoma." (PMID 38077402, 2023).
lymphocytic colitis (5 papers, 2014 to 2025). Microscopic colitis characterized by the accumulation of lymphocytes in the colonic epithelium and lamina propria. "It points to a mechanism of TNF-α-dependent decrease in claudin-5 in the colon mucosae of lymphocytic colitis patients, as TNF-α release was evident in colonic epithelial HT-29 cells following C. concisus infection." (PMID 33669494, 2021). "It has been shown that pro-inflammatory cytokines, such as TNF-α and IL-15, alter CLDN8 expression and distribution, resulting in lymphocytic colitis, which is characterized by epithelial barrier impairment, leak-flux diarrhea, and abnormal fluid absorption." (PMID 41321497, 2025).
macrosomia (5 papers, 2020 to 2024). "Probiotics also reduced the level of inflammatory markers (high-sensitivity C-reactive protein, interleukin-6, tumor necrosis factor-α, and malondialdehyde), incidence of macrosomia, and newborn hospitalization." (PMID 34578921, 2021). "There was a positive correlation between P0 macrosomia and the hepatic TNF-α mRNA levels in ethanol-fed mice at E15.5, whereas offspring growth at P21 was negatively associated with the TNF-α mRNA levels." (PMID 32572070, 2020). "An intervention of low GI advice had no impact on levels of CRP in women with a high risk of GDM nor on IL-6 and TNF-α in women at high risk for macrosomia in the second half pregnancy." (PMID 33806342, 2021).
membranous nephropathy (5 papers, 2017 to 2023). "Active membranous glomerulonephritis leads to not only proteinuria but also increased urinary TNF excretion." (PMID 34135910, 2021). "However, inhibition of TNF signaling might attenuate kidney immune cell infiltration in experimental membranous nephropathy." (PMID 34135910, 2021).
MRSA pneumonia (5 papers, 2013 to 2025). "MRSA pneumonia was associated with high concentrations in BALF of proinflammatory cytokines (TNF-α, IL-6) and chemokines (CXCL2, CXCL5)." (PMID 35972289, 2022). "However, IFN-γ also drives fatal lung inflammation during MRSA pneumonia by promoting the overproduction of inflammatory cytokines, such as TNF-α." (PMID 36830716, 2023). "MRSA pneumonia induced an increase in IL-6, G-CSF, TNFα, IL-1β, and IL-10." (PMID 24204769, 2013).
myelitis (5 papers, 2022 to 2026). An inflammatory process affecting the spinal cord. "Reports of TNF-inhibitor-associated myelitis evolving into longitudinally extensive, steroid-refractory disease remain limited, and this presentation may broaden the recognized clinical spectrum of TNF-α-related CNS inflammatory events." (PMID 42187520, 2026).
neuralgia (5 papers, 2015 to 2025). "In the rat model of postherpetic neuralgia, THSWD has an analgesic effect on postherpetic neuralgia in rats by inhibiting the release of inflammatory factors such as tumor necrosis factor-α (TNF-α) and interleukin-1β (IL-1β) and reducing the apoptosis of spinal nerve cells." (PMID 34447315, 2021). "In a recent study, on the effects of intrathecal injection of methylprednisolone on postherpetic neuralgia, CSF IL-8 increased 8–9 times while the cyto/chemokines IL-1, IL-10, and TNF-α were not affected over time, compared to controls." (PMID 30261896, 2018).
neurotoxicity (5 papers, 2016 to 2025). Toxicity that causes injury to the central or peripheral nervous system or damages its function. "Neurotoxicity is a pathological phenomenon seen in neuroHIV that was also observed through transfer of cell-free CM from Ephb2 activated microglia onto neurons, which our data suggest is a consequence of the assortment of pro-inflammatory secreted factors (IL-6, CXCL10, TNFα, IL-1β etc.)." (PMID 40588746, 2025).
otitis (5 papers, 2019 to 2025). "Similarly, cinnamtannin B1, a trimeric A-type procyanidin, inhibits the O2•− generation and ELA-2 release by human neutrophils and reduces the infiltration of the immune cells and TNF-α and IL-6 release in vivo, e.g., in a mice ear infection model." (PMID 35630834, 2022). "Furthermore, TLR2 deficiency leads to a decreased proinflammatory cytokine profile, including TNF and IL-1β, in a murine model of S. pneumoniae otitis, resulting in increased bacterial outgrowth, bacteraemia and death." (PMID 31700009, 2019). "Tumor necrosis factor alpha (TNF-α), IL-1β, and IL-8 are commonly identified in MEE samples from patients with chronic OM, and otitis-prone children have lower expression of IL-6 and IL-8 in their MEEs (4, 21, –, 23)." (PMID 32661126, 2020). "TLR-1, -2, -4, -5, -6, -9; IL-6, -8, -10, -12; IFN-γ; TNF-α; and NOS mRNA expression was measured in effusions from both otitis-prone and non-otitis-prone groups." (PMID 40227356, 2025).
otulipenia (5 papers, 2016 to 2023). "Hypomorphic mutations in the OTULIN gene, resulting in elevated NFKB activity, cause ORAS, also named “otulipenia”, which is characterized by inflammatory skin signs with panniculitis starting during the neonatal period and responding to TNF inhibitors." (PMID 35883675, 2022). "Interestingly, homozygous loss-of-function mutations in the OTULIN gene cause an auto-inflammatory condition, called ORAS (OTULIN-related inflammatory syndrome) or otulipenia that is responsive to anti-TNF treatment." (PMID 31998699, 2019). "Here, we describe that a homozygous hypomorphic OTULIN mutation in a consanguineous family causes a potentially fatal autoinflammatory disorder termed OTULIN-related autoinflammatory syndrome (ORAS), which can be managed by Infliximab (anti-TNF neutralizing antibody)." (PMID 27523608, 2016).
Ovarian cyst (5 papers, 2017 to 2024). The presence of one or more cysts of the ovary. "Regarding immunohistochemical analysis, the expression of TNF-α in granulosa layer and follicular fluid of follicles and ovarian cysts in PCOS group was more than the control group’s expression." (PMID 29201665, 2017). "denoted an increased expression of IL-6 and TNF-α in the fluid of cystic ovaries in the untreated group, providing this may be related to the presence of follicular cysts." (PMID 39495423, 2024). "In addition, the role of TNF-α and ROS in the pathogenesis of ovarian cysts, the increase in the number of ovarian atretic follicles, and the decrease in the volume of corpus luteum has been reported in previous studies." (PMID 32787839, 2020). "The results showed decreased IL-6 and CRP, and interestingly, they observed decreased expression of tumor necrosis factor alpha (TNF-α) in the granulosa layer and follicular fluid of follicles and ovarian cysts in the PCOS group treated with curcumin." (PMID 34959992, 2021). "In the present study, we found that TNF, IL6, and IL1B were all involved in the NOD-like receptor signaling pathway, which may provide a new field for Jingshu granules in the treatment of ovarian cysts." (PMID 33623786, 2021).
overlap syndrome (5 papers, 2016 to 2025). "The few patients who had post-rituximab immunosuppression using obinutuzumab, belimumab, tocilizumab, Janus kinase inhibitors or TNF-α blockers were under occasional special circumstances, mostly due to an overlap syndrome (e.g. RA)." (PMID 40372703, 2025). "Therefore, we examined the NET-inducing activity of SLE/AAV overlap syndrome in patient’s serum in two ways, using both unstimulated and TNF-α-stimulated neutrophils from healthy subjects." (PMID 35025058, 2022).
pancolitis (5 papers, 2015 to 2025). Ulcerative colitis that involves the entire colon. "In our cohort, only one patient needed colectomy after SOT because of refractory pancolitis despite anti-TNF maintenance treatment with infliximab." (PMID 26288187, 2015). "Most patients suffered from pancolitis (59.4%) and were treated with UPA after the failure of anti-TNFα plus anti-integrin or anti-IL12/23 (63.4%)." (PMID 41227197, 2025).
pancreatic neuroendocrine tumor (5 papers, 2020 to 2025). Pancreatic endocrine tumor, also known as pancreatic neuroendocrine tumor (PNET), describes a group of endocrine tumors originating in the pancreas that are usually indolent and benign, but may have the potential to be malignant. "For example, octreotide (OCT), a synthetic analog of somatostatin, was exposed on AAVP for the delivery of tumor necrosis factor (TNF) to somatostatin receptor type-2 (SSTR-2) expressing pancreatic neuroendocrine tumors." (PMID 33671476, 2021). "In our study among patients with NET, the concentrations of TNF-α were significantly higher in those with pancreatic NET (panNET) compared to other subtypes of NET (p = 0.040), suggesting an association between the location of the primary tumor and the systemic inflammatory response." (PMID 40507492, 2025). "The use of octreotide, a synthetic analogue of somatostatin, as the targeting ligand of the AAVP vector, provided the highly selective delivery of tumor necrosis factor α (TNF-α) to pancreatic neuroendocrine tumor cells expressing surface somatostatin receptors." (PMID 36430720, 2022). "Our experiments in BON-1 cells derived from a pancreatic NET revealed significant treatment-related increase in TNFα synthesis paralleled by a significant reduction in IL-6 and IL-10 expression; this cytokine profile reflects the ability of lanreotide to induce a Th1 cytotoxic immune-response." (PMID 32766136, 2020).
papilledema (5 papers, 2010 to 2025). "In the first case, joint involvement and fever were resolved with anti-TNF agents; yet, the urticarial rash did not respond to this therapy, and optic disc edema occurred during the anti-TNF therapy." (PMID 35281325, 2022).
parasite (5 papers, 2018 to 2025). "The authors did, however, uncover upregulation of TNF-α mRNA in macrophages following tachyzoite exposure, indicating the comparative lack of IL-12 protein production observed was not due to an inability to detect the parasite infection." (PMID 34576723, 2021).
pituitary tumor (5 papers, 2014 to 2023). A benign or malignant neoplasm affecting the pituitary gland. "However, it is still unclear whether TNFα is a direct mechanism causing apoplexy in pituitary tumors or just a consequence of hemorrhagic transformation and hypoxia." (PMID 37958474, 2023). "In mouse pituitary tumor cells, TNFα upregulates VEGF and MMP-9, thus stimulating hemorrhagic transformation." (PMID 37958474, 2023). "Also, HN inhibited the apoptotic effect of TNF-α on pituitary tumor cells." (PMID 25360890, 2014).
protozoal infections (5 papers, 2016 to 2025). "Some studies have shown a remarkable elevation in IL-1β, IL-6, IFN-γ, and TNF-α cytokines in systemic protozoal diseases in cattle." (PMID 36679958, 2023). "IFN-γ, a cytokine critical for innate and adaptive immune responses against viral and protozoal infections, activates HMC3 to release pro-inflammatory cytokines, including TNF-α, IL-1β and IL-6, all of them are important transcriptional regulator of inflammasome pathways." (PMID 34106880, 2021). "Although TNF-α and IFN-γ are both immunomodulating and proinflammatory cytokines, TNF-α secretion by activated macrophages is via bacterial lipopolysaccharide, whereas, IFN-γ is critical for innate and adaptive immunity against viral, some bacterial, and protozoal infections." (PMID 29903699, 2018).
pyometra (5 papers, 2009 to 2025). "Given the wide implication of TNF during the host response to a plethora of pathogens, it was expected that pyometra would be associated with robust upregulation of TNF." (PMID 19956711, 2009). "Accordingly, the IL1B and IL8 genes were detected as overexpressed in pyometra group, being IL1B, IL6 and TNF overexpressed particularly in pyometra of hormone-treated animals." (PMID 26222498, 2015). "In contrast, the pro-inflammatory TNF gene was identified as a central gene in pyometra of hormone-treated dogs." (PMID 26222498, 2015). "Considering that TNF has a pivotal role in inflammation, therapies targeting TNF could be considered in pyometra." (PMID 26222498, 2015). "(2014), TNF‐α, IFN‐γ, IL‐2, IL‐4 and IL‐10 cytokine concentrations were found to be high in dogs with pyometra." (PMID 39792082, 2025). "However, in another study, no increase in these cytokines (TNF‐α and IL‐10) was observed in dogs with pyometra." (PMID 39792082, 2025).
renal cell adenocarcinoma (5 papers, 2018 to 2023). A carcinoma arising from the renal parenchyma. "The growth of renal cell cancer cells can be inhibited by the activation of TNF signaling pathway through the silencing gene VCAN." (PMID 33015179, 2020). "Although many cells are sensitive to TNF in the presence of the TAK1 kinase inhibitor 5Z-7-oxozeaenol (hereafter referred to as TAK1i), we focused our attention on a cell line that is largely resistant to this treatment combination, namely, the renal cell adenocarcinoma 786-0." (PMID 29642005, 2018).